HSD17B10 (hydroxysteroid 17-beta dehydrogenase 10)
Description:
Mitochondrial dehydrogenase involved in pathways of fatty acid, branched-chain amino acid and steroid metabolism. Acts as (S)-3-hydroxyacyl-CoA dehydrogenase in mitochondrial fatty acid beta-oxidation, a major degradation pathway of fatty acids. Catalyzes the third step in the beta-oxidation cycle, namely the reversible conversion of (S)-3-hydroxyacyl-CoA to 3-ketoacyl-CoA. Preferentially accepts straight medium- and short-chain acyl-CoA substrates with highest efficiency for (3S)-hydroxybutanoyl-CoA. Acts as 3-hydroxy-2-methylbutyryl-CoA dehydrogenase in branched-chain amino acid catabolic pathway. Catalyzes the oxidation of 3-hydroxy-2-methylbutanoyl-CoA into 2-methyl-3-oxobutanoyl-CoA, a step in isoleucine degradation pathway. Has hydroxysteroid dehydrogenase activity toward steroid hormones and bile acids. Catalyzes the oxidation of 3alpha-, 17beta-, 20beta- and 21-hydroxysteroids and 7alpha- and 7beta-hydroxy bile acids. Oxidizes allopregnanolone/brexanolone at the 3alpha-hydroxyl group, which is known to be critical for the activation of gamma-aminobutyric acid receptors (GABAARs) chloride channel. Has phospholipase C-like activity toward cardiolipin and its oxidized species. Likely oxidizes the 2'-hydroxyl in the head group of cardiolipin to form a ketone intermediate that undergoes nucleophilic attack by water and fragments into diacylglycerol, dihydroxyacetone and orthophosphate. Has higher affinity for cardiolipin with oxidized fatty acids and may degrade these species during the oxidative stress response to protect cells from apoptosis. By interacting with intracellular amyloid-beta, it may contribute to the neuronal dysfunction associated with Alzheimer disease (AD). Essential for structural and functional integrity of mitochondria. In addition to mitochondrial dehydrogenase activity, moonlights as a component of mitochondrial ribonuclease P, a complex that cleaves tRNA molecules in their 5'-ends. Together with TRMT10C/MRPP1, forms a subcomplex of the mitochondrial ribonuclease P, named MRPP1-MRPP2 subcomplex, which displays functions that are independent of the ribonuclease P activity. The MRPP1-MRPP2 subcomplex catalyzes the formation of N(1)-methylguanine and N(1)-methyladenine at position 9 (m1G9 and m1A9, respectively) in tRNAs; HSD17B10/MRPP2 acting as a non-catalytic subunit. The MRPP1-MRPP2 subcomplex also acts as a tRNA maturation platform: following 5'-end cleavage by the mitochondrial ribonuclease P complex, the MRPP1-MRPP2 subcomplex enhances the efficiency of 3'-processing catalyzed by ELAC2, retains the tRNA product after ELAC2 processing and presents the nascent tRNA to the mitochondrial CCA tRNA nucleotidyltransferase TRNT1 enzyme. Associates with mitochondrial DNA complexes at the nucleoids to initiate RNA processing and ribosome assembly.
Synonyms: MHBD; ERAB; HADH2; MRPP2; SCHAD; SDR5C1; 17b-HSD10; ABAD; CAMR; DUPXp11.22; HCD2; HSD10MD; MRX17; MRX31; MRXS10
Tractability: Small molecule: a structure with a bound ligand is known; a high-quality ligand is known; it has a high-quality binding pocket; it belongs to a druggable protein family. Antibody: its Gene Ontology location is reachable by antibodies, with high confidence. PROTAC: ubiquitination databases record sites on it; its protein half-life has been measured; a small molecule that binds it is known.
Target class: Enzyme; Oxidoreductase
Safety:
Unwanted effects reported when the protein is acted on. In parentheses: how it was acted on, where the effect was seen, and who reports it.
Increased, Liver Steatosis (inhibition; source: AOP-Wiki)
Gene: Protein-coding gene on chromosome X (53,431,258 to 53,434,371, reverse strand). Ensembl gene ENSG00000072506.
Subcellular location: Mitochondrion; Mitochondrion matrix, mitochondrion nucleoid
Pathways (Reactome):
Metabolism of RNA: rRNA processing in the mitochondrion; tRNA modification in the mitochondrion; tRNA processing in the mitochondrion
Metabolism: Branched-chain amino acid catabolism
Metabolism of proteins: Mitochondrial protein degradation
Gene Ontology:
Molecular function: (3S)-3-hydroxyacyl-CoA dehydrogenase (NAD+) activity; 17-beta-hydroxysteroid dehydrogenase (NAD+) activity; 3-hydroxy-2-methylbutyryl-CoA dehydrogenase activity; cardiolipin dehydrogenase (NAD+) activity; chenodeoxycholate 7-alpha-dehydrogenase (NAD+) activity; cholate 7-alpha-dehydrogenase (NAD+) activity; estradiol 17-beta-dehydrogenase [NAD(P)+] activity; isoursodeoxycholate 7-beta-dehydrogenase (NAD+) activity; protein binding; RNA binding; testosterone dehydrogenase (NAD+) activity; tRNA binding; ursodeoxycholate 7-beta-dehydrogenase (NAD+) activity; alcohol dehydrogenase (NAD+) activity; androstan-3-alpha,17-beta-diol dehydrogenase (NAD+) activity; long-chain (3S)-3-hydroxyacyl-CoA dehydrogenase (NAD+) activity
Biological process: androgen metabolic process; bile acid biosynthetic process; brexanolone metabolic process; C21-steroid hormone metabolic process; estrogen metabolic process; fatty acid beta-oxidation; L-isoleucine catabolic process; mitochondrial tRNA 3'-end processing; mitochondrial tRNA 5'-end processing; mitochondrial tRNA methylation; mitochondrion organization; protein homotetramerization; tRNA 3'-end processing; tRNA 3'-terminal CCA addition; fatty acid metabolic process; lipid metabolic process
Cellular component: catalytic complex; endoribonuclease complex; mitochondrial nucleoid; mitochondrial ribonuclease P complex; mitochondrion; tRNA methyltransferase complex; cytoplasm; mitochondrial matrix; plasma membrane
Gene-disease validity (ClinGen):
ClinGen rates the evidence that HSD17B10 causes each of these diseases.
HSD10 mitochondrial disease (X-linked): Definitive.
Homologues: Orthologues: chimpanzee HSD17B10 (100% identical), macaque HSD17B10 (97% identical), guinea pig HSD17B10 (92% identical), dog HSD17B10 (92% identical), pig HSD17B10 (91% identical), rabbit HSD17B10 (90% identical), mouse Hsd17b10 (88% identical), rat Hsd17b10 (85% identical), tropical clawed frog hsd17b10 (76% identical), zebrafish hsd17b10 (74% identical), Drosophila melanogaster scu (67% identical), Caenorhabditis elegans ard-1 (59% identical). Paralogues in human: HSD17B8 (33% identical), HSD17B4 (28% identical), RDH5 (27% identical), HSD17B14 (25% identical), RDH16 (25% identical), SDR9C7 (24% identical), DHRS9 (23% identical), HSD17B1 (23% identical), HSD11B2 (21% identical), HSD17B6 (21% identical), RDH10 (21% identical), SDR16C5 (21% identical), and 13 more.